HDAC1 (histone deacetylase 1)
Diseases named in the same sentence as HDAC1 in open-access papers (continued):
Sharing a sentence is not in itself a finding about the gene and the disease.
thymic lymphoma (2 papers, 2019 to 2022). "Cell lines derived from Hdac1‐deficient thymic lymphomas undergo apoptosis upon DOT1L inhibition or depletion, which indicates a form of non‐oncogene addiction to DOT1L." (PMID 31304633, 2019). "Our analysis of Hdac1‐deficient thymic lymphoma cells ex vivo provided more insight into the possible mechanisms for the reduced tumor burden." (PMID 31304633, 2019). "This regulation is relevant in a cancer context, since heterozygous deletion of Dot1L prolongs the survival of mice that develop Hdac1‐deficient thymic lymphomas." (PMID 31304633, 2019). "To further study the Dot1L dependence of Hdac1‐deficient thymic lymphomas in a more controlled environment, we turned to ex vivo experiments." (PMID 31304633, 2019). "Thus, shRNA‐mediated DOT1L knockdown and chemical DOT1L inhibition showed that the Hdac1‐deficient thymic lymphoma cell lines depended on DOT1L activity." (PMID 31304633, 2019). "Thus, DOT1L inhibition induced apoptosis specifically in Hdac1‐deficient thymic lymphoma cell lines." (PMID 31304633, 2019). "Cell lines were derived from Hdac1‐deficient thymic lymphomas." (PMID 31304633, 2019). "Mice with conditional Hdac1 alleles but wild type for Dot1L (Lck‐Cre;Hdac1f/f) developed thymic lymphomas for which they had to be sacrificed, with a median latency of 21 weeks and an incidence of 86% during the 40‐week length of the experiment, comparable to what was observed before." (PMID 31304633, 2019). "In the mouse, thymic lymphoma cell lines derived from conditional Hdac1 knock-out mice also show increased H3K79me and this coincides with increased sensitivity towards DOT1L inhibitors." (PMID 36425063, 2022). "In mouse thymic lymphoma, HDAC1 deletion results in oncogenic transformation, whereas in the case of CTCL reduced HDAC activity has tumor-suppressing consequences." (PMID 36425063, 2022). "Heterozygous Dot1L deletion prolonged the survival of mice with thymocyte‐specific Hdac1 deletion due to a lower incidence and increased latency of thymic lymphomas." (PMID 31304633, 2019). "Thus, the effect of HDAC1 on H3K79 methylation observed in vivo in 3‐week‐old pre‐malignant thymuses was maintained in the thymic lymphoma cell lines." (PMID 31304633, 2019). "Interestingly, homozygous Dot1L deletion, leading to a complete loss of H3K79me, did not extend the latency of thymic lymphomas (81% incidence, 15.7‐week median latency, comparison to Hdac1 deletion alone P = 0.463)." (PMID 31304633, 2019). "In summary, we identified an evolutionarily conserved crosstalk between HDAC1 and DOT1L with impact in murine thymic lymphoma development." (PMID 31304633, 2019). "HDAC1 negatively regulates DOT1L activity in yeast, mouse thymocytes, and mouse thymic lymphoma." (PMID 36425063, 2022). "Since Hdac1 deletion in thymocytes resulted in an increase in H3K79 methylation, as well as thymic lymphoma formation, we asked whether increased H3K79 methylation was important for tumor development in this mouse model." (PMID 31304633, 2019).
abdominal aortic aneurysm (1 paper, 2020). Enlargement and ballooning of the vessel that supplies arterial blood to the abdomen, pelvis and legs. "Recently, it has been shown that in ApoE gene-knockout mice with abdominal aortic aneurysms, infusion of ANG II for 4 weeks increased expression of class I HDAC1, 2, and 3, as well as expression of class II HDAC 4 and 7; it also decreased acetylation levels of H3-K1873." (PMID 32152395, 2020).
age-related macular degeneration (1 paper, 2015). Age-related loss of vision in the central portion of the retina (macula), secondary to retinal degeneration. "Human neural retina concentrations of HDAC1, 2, HDAC5, HDAC6, and HDAC7 decreased in age-related macular degeneration (AMD)-affected donors and exhibited a greater decrease in AD-affected donors in comparison to age-matched control neural retinas." (PMID 25962138, 2015).
alcohol addiction (1 paper, 2015). "Our data presented here are in line with the reduction of ethanol-induced behaviors by HDAC inhibitors and are the first to demonstrate that the specific inhibition of HDAC1 is also efficient and support the notion that alcohol addiction may involve epigenetic modifications." (PMID 25762717, 2015).
amyloid (1 paper, 2025). "In line with this, a recent study found that genetic ablation of microglial HDAC1 and HDAC2 in an AD mouse model reduced amyloid plaque burden and rescued memory deficits, suggesting HDAC modulation in microglia as a potential therapeutic target." (PMID 40300607, 2025).
anaplastic oligoastrocytoma (1 paper, 2021). An oligoastrocytoma characterized by the presence of increased cellularity, nuclear atypia, pleomorphism, and high mitotic activity. "HDAC1 mRNA over-expression in anaplastic oligoastrocytoma (n = 4) reached a fold change (FC) of 2.56 compared with the normal tissues (n = 6) (p = 4.41E-04)." (PMID 34540896, 2021).
Atrophy (1 paper, 2015). Any weakening or degeneration, especially through lack of use. "If sarcopenia results from lack of exercise and movement during aging, inhibition of HDAC1 will prevent muscle atrophy." (PMID 26290460, 2015).
Azoospermia (1 paper, 2021). Absence of any measurable level of sperm,whereby spermatozoa cannot be observed even after centrifugation of the semen pellet. "A study conducted by Jee Hyun Kim in 2014 showed that the level of HDAC1 expression in men with azoospermia was lower than that of normal people and attributed it to the reduction of HDAC1 gene expression with sperm DFI." (PMID 34400949, 2021).
basal cell carcinoma (1 paper, 2024). A carcinoma involving the basal cells. "The combination therapy of HDAC1 and aPKC inhibitors has been shown to prevent GLI1 nuclear maturation and effectively antagonize basal cell carcinoma (BCC) at lower doses than either agent alone." (PMID 38498906, 2024).
brain glioblastoma (1 paper, 2022). A WHO grade IV malignant astrocytic tumor that arises from the brain, usually the cerebral hemispheres. "TCGA statistics revealed that HDAC1 expression was 3.131-fold higher (p = 3.08E-8) in ductal brain glioblastoma than in normal tissues." (PMID 35359455, 2022).
carcinoma in situ (1 paper, 2014). "HDAC-1 to 3 and Ki-67 were correlated with clinico-pathologic characteristics (stage, grading, adjacent carcinoma in situ, multiplicity and growth pattern) of the tumours." (PMID 24624923, 2014). "Strong staining of HDAC-1 and HDAC-2 was associated with higher grading (both WHO 1973 and 2004), additionally tumours with high expression levels of HDAC-2 presented more often with adjacent carcinoma in situ compared to tumours with weak HDAC-2 staining." (PMID 24624923, 2014).
Cerebral atrophy (1 paper, 2018). Atrophy (wasting, decrease in size of cells or tissue) affecting the cerebrum. "Conversely, TOPK siRNA down-regulated M2 marker, aggravated cerebral atrophy, as well as the sensorimotor functions, which was completely reversed by the selective HDAC1/HDAC2 specific inhibitor FK228." (PMID 29896413, 2018).
Cholecystitis (1 paper, 2022). The presence of inflammatory changes in the gallbladder. "As shown by bioinformatics analysis and immunohistochemical detection, high HDAC1 expression was witnessed in CC tissues relative to matched controls from patients with cholecystitis." (PMID 35395834, 2022).
chromophobe carcinoma (1 paper, 2021). "For example, in RCC (including chromophobe carcinoma, ccRCC, and papillary cell carcinoma), low expression of HDAC1, HDAC2, HDAC3, HDAC8, HDAC10 and high expression of HDAC5, HDAC7, HDAC11 have longer survival time." (PMID 34308568, 2021).
chronic hepatitis B (1 paper, 2019). "A clinical study has shown that the activities of HDAC1 and HDAC2 are obviously elevated in the patients with chronic hepatitis B, especially in the patients with liver failure." (PMID 31183000, 2019).
colorectal tumours (1 paper, 2006). "For example, HDAC1 overexpression was seen in renal, bladder, colorectal tumour and normal tissues, and a small proportion of ovarian primary tumours." (PMID 16638127, 2006).
diabetic foot ulcers (1 paper, 2025). "Further, in patients with diabetic foot ulcers it was found that HDAC1, 3, 4 and 11 were upregulated." (PMID 41369370, 2025).
dialysis (1 paper, 2021). "Additionally, the mesothelial cells (MCs) isolated from effluent of peritoneal dialysis (PD) patients were treated with MS-275, a HDAC1–3 inhibitor, and downregulated mesenchymal markers including TGF-β1 to promote EMT reversal." (PMID 33414476, 2021).
Down syndrome (1 paper, 2016). "For example, in sample from donor D4 (carrying Down's syndrome), where MSCs senescence process was delayed, DNMT1 and HDAC1 expression remained higher than in other samples at the same passage (p8)." (PMID 27803714, 2016).
Friedreich ataxia (1 paper, 2018). An inherited condition that affects the nervous system and causes movement problems. "This compound has a Ki value of 14 nM for HDAC3, which was 10 times lower than the Ki for HDAC1, while its analog, RGFP109, which is also used as a promising treatment for Friedreich’s ataxia, shows a better potency for HDAC3 with the Ki value of 5 nM, and 32 nM for HDAC1." (PMID 29498635, 2018).
Fulminant hepatitis (1 paper, 2024). Acute hepatitis complicated by acute liver failure with hepatic encephalopathy occurring less than 8 weeks after the onset of jaundice. "Previous studies have reported implications of MDM2 and COP1 that targeted STAT3 for degradation in tumorigenesis, and involvement of MDM2 in RACK1-abrogated HDAC1 degradation during the pathogenesis of fulminant hepatitis." (PMID 39024388, 2024).
fungal infection (1 paper, 2019). "Taken together, the data suggests that fungal infection is regulated by histone acetylation and deacetylation and the increased expression of HDAC1 and hypoacetylation may contribute to the pathogenesis of fungal keratitis." (PMID 31285488, 2019).
fungal keratitis (1 paper, 2019). "We found that the downregulation of histone acetylation and upregulation of HDAC1 expression were associated with the increased inflammation response in fungal keratitis not only in humans but also in experimental animals." (PMID 31285488, 2019). "Our results showed that the downregulation of histone acetylation and upregulation of HDAC1 expression were associated with the increased inflammatory response in fungal keratitis." (PMID 31285488, 2019). "From this result, we therefore assumed that the downregulation of AC-H3 and the upregulation of HDAC1 in fungal keratitis might be implicated in the pathogenesis of the disease." (PMID 31285488, 2019). "In the current study, we found that HDAC1 was highly expressed in corneal specimens from human with fungal keratitis and mice with experimental fungal keratitis." (PMID 31285488, 2019). "In contrast, a strong expression of HDAC1 was demonstrated in cornea specimens from human and mice with fungal keratitis." (PMID 31285488, 2019). "Reduced acetylated histone H3 (AC-H3) expression and increased HDAC1 expression in the corneal sections of human fungal keratitis and experimental fungal keratitis in mice compared with control were demonstrated by immunohistochemistry." (PMID 31285488, 2019). "Importantly, the decreased AC-H3 was restored after SAHA treatment, while the HDAC1 was significantly reduced in the corneas of mice with fungal keratitis with the application of HDAC inhibitor-SAHA." (PMID 31285488, 2019). "In the current study, we investigated the expression of histone H3 (H3), acetylated histone H3 (AC-H3), HDAC1, TLR4, TNFα, and IL-1β in corneal specimens from patients with fungal keratitis and mice with experimental fungal keratitis." (PMID 31285488, 2019).
glomerular diseases (1 paper, 2023). "VPA can specifically inhibit HDAC1 and HDAC2, and previous studies have demonstrated that VPA treatment improves AKI, glomerular diseases, and UUO in mice." (PMID 37153759, 2023).
gonococcal infection (1 paper, 2020). "In contrast, gonococcal infection downregulated expression of the human HDAC1-encoding gene compared to uninfected monocytes." (PMID 32085531, 2020). "Of note, gonococcal infection in macrophages downregulated the expression of human HDAC1, the most commonly expressed human HDAC in myeloid cells, suggesting epigenetic modulation." (PMID 32085531, 2020).
gout (1 paper, 2019). A condition characterized by painful swelling of the joints, which is caused by deposition of urate crystals. "Although romidepsin is a very potent inhibitor in vitro, more studies are required before we can achieve HDAC1/2 inhibition during a gout flare in patients." (PMID 30728075, 2019). "Here, we identify the simultaneous inhibition of HDAC1 and HDAC2 as a possible new treatment option in acute gouty arthritis." (PMID 30728075, 2019).
hematoma (1 paper, 2026). A hematoma is a collection of blood from a vascular structure into an extravascular space. "In this study, we observed that knockout of HDAC1/2 in microglia alleviated neurological deficits caused by ICH, preserved white matter integrity, and accelerated hematoma clearance post-ICH." (PMID 41632031, 2026).
histiocytic lymphoma (1 paper, 2021). "Given previous studies, N-(2-aminophenyl)benzamide acridine (8a), as a histone deacetylase 1 (HDAC1) inhibitor, induces apoptosis and shows significant anti-proliferative activity against histiocytic lymphoma U937 cells." (PMID 34073721, 2021).
Hyperchloremia (1 paper, 2020). An abnormally increased chloride concentration in the blood. "The whole-nephron HDAC1/HDAC2-deficient animals had the most severe imbalances, presenting with significant hypernatremia/hyperchloremia and death within 30 days of knockdown." (PMID 32673289, 2020).
idiopathic pulmonary fibrosis (1 paper, 2024). Idiopathic pulmonary fibrosis (IPF) is a nonneoplastic pulmonary disease that is characterized by the formation of scar tissue within the lungs in the absence of any known cause. "Furthermore, the expression levels of HDAC1 and HDAC2 are significantly elevated in fibrotic lesions of idiopathic pulmonary fibrosis (IPF) lung tissues and primary IPF fibroblasts." (PMID 39193364, 2024).
kidney injury (1 paper, 2020). Trauma to the kidney. "In the present study, we demonstrate that 7-HC is an effective nephroprotective agent against colistin-induced kidney injury and the protective effect was achieved through the decreased level of HDAC1 and the activation of Nrf2 signaling pathway." (PMID 32848758, 2020).
lymphedema (1 paper, 2017). Excess fluid collection in tissues, causing swelling. "Our results demonstrate that endothelial inactivation of ubiquitously expressed Hdac3, but not Hdac1 or Hdac2, in mice causes embryonic lethality, failure of blood-lymph separation, lymphedema, and defects in both lymphatic and lymphovenous valves." (PMID 29035278, 2017).
lymphoblastic lymphoma (1 paper, 2025). A lymphoma composed of immature small to medium-sized precursor lymphoid cells (lymphoblasts). "Similarly, complete loss of HDAC1 and HDAC2 in thymocytes results in a block in T cell development, while gradual loss of HDAC activity induces lymphoblastic lymphoma." (PMID 40175628, 2025).
macrocephalus (1 paper, 2021). "HDAC1 valproic acid inhibition and GSK3B lithium upregulate the Wnt transcription inhibition and lead to macrocephalus." (PMID 34877571, 2021).
male infertility (1 paper, 2010). The inability of the male to effect fertilization of an ovum after a specified period of unprotected intercourse. "Inhibition of histone deacetylase-1 results in male infertility through apoptosis in spermatogonia and spermatocytes." (PMID 20539761, 2010).
metastatic tumor (1 paper, 2021). "The significantly elevated expression levels of HDAC1, HDAC2, and HDAC3 (HDAC1–3) have also been reported in several human OS cell lines and primary and metastatic tumor samples." (PMID 34439353, 2021).
migraine (1 paper, 2023). "Differentially methylated CpGs were also detected in the genes HDAC1 and HDAC3 among sites with nominal association (p < 0.05) with reduced headache and migraine days in our study." (PMID 38087366, 2023).
monoclonal gammopathy of undetermined significance (1 paper, 2021). "HDAC1 expression reduced in patients with monoclonal gammopathy of undetermined significance (MGUS)." (PMID 33663586, 2021).
myasthenia gravis (1 paper, 2025). Myasthenia gravis (MG) is a rare, clinically heterogeneous, autoimmune disorder of the neuromuscular junction characterized by fatigable weakness of voluntary muscles. "Collectively, our results suggest that interferon regulatory factor 1 enhances T cell differentiation by recruiting histone deacetylase 1 to block B cell CD180 transcription in myasthenia gravis via the Toll-like receptor 4/mitogenactivated protein kinases/nuclear factor-kappa B pathway." (PMID 41169211, 2025).
myeloid neoplasm (1 paper, 2022). Proliferation of myeloid cells originating from a primitive stem cell. "Despite the promising pre-clinical activity, single-agent HDAC1/2 inhibitors have had limited clinical success to date in myeloid neoplasms." (PMID 36077629, 2022).
nephritis (1 paper, 2008). Inflammation of renal tissue. "Although Mier1 expression and Hdac1 functions in B cells are not well characterized, Hdac1 is ubiquitously expressed in lymphoid tissues, and Hdac inhibitors have been used to induce cell cycle arrest and downregulate inflammatory cytokines and nephritis in MRL/lpr lupus mice." (PMID 19578517, 2008).
nevus (1 paper, 2007). Nevus (or naevus, plural nevi or naevi, from nævus, Latin for "birthmark") is the medical term for sharply circumscribed[1] and chronic lesions of the skin or mucosa. "Here we show that HDAC1 is prominently detected in p16INK4a-positive, senescent intradermal melanocytic nevi but not in proliferating, recurrent nevus cells that localize to the epidermal/dermal junction." (PMID 17578512, 2007).
non‐alcoholic steatohepatitis (1 paper, 2023). "Methyltransferase METTL3 in non‐alcoholic steatohepatitis (NASH) could induce the deacetylation of H3K27 and H3K9 by recruiting HDAC1/2 on the CCL2 promoter, thus inhibiting the expression of CCL2 and inhibiting the progression of NASH." (PMID 36872292, 2023).
nutritional deficiency (1 paper, 2022). "Among them, HDAC1 has been shown to promote skeletal muscle atrophy in response to nutritional deficiency." (PMID 35741361, 2022). "It was found that, in the case of nutritional deficiency, HDAC1 activates autophagy, thereby promoting skeletal muscle atrophy." (PMID 35741361, 2022).
ovarian disorder (1 paper, 2026). A disease involving the ovary. "Our findings indicate that PAE reduces ovarian reserve through HDAC1-linked epigenetic silencing of Usp9x, exacerbating HIF1α/NOBOX pathway dysfunction, thereby informing aspirin's gestational safety and future interventions for fetal-origin ovarian disorders." (PMID 41524225, 2026).
pancreatitis (1 paper, 2022). Inflammation of the pancreas.
papilloma (1 paper, 2013). A benign epithelial neoplasm that projects above the surrounding epithelial surface and consists of villous or arborescent outgrowths of fibrovascular stroma. "In particular, the impaired activity of the Sin3A co-repressor complex and the concomitant overexpression of the c-Myc in HDAC1- but not HDAC2-deficient papillomas provide strong evidence for crucial function for Sin3A and HDAC1 as a negative regulator of the proto-oncogene c-Myc." (PMID 24240174, 2013).
plaque psoriasis (1 paper, 2020). "Next, we compared the expression of HDAC1, SIRT1, p63, and PCNA in guttate and plaque psoriasis." (PMID 32825671, 2020).